TPRN (taperin)
Description:
Essential for hearing (By similarity). Required for maintenance of stereocilia on both inner and outer hair cells (By similarity). Necessary for the integrity of the stereociliary rootlet (By similarity). May act as an actin cytoskeleton regulator involved in the regulation of actin dynamics at the pointed end in hair cells (By similarity). Forms rings at the base of stereocilia and binds actin filaments in the stereocilia which may stabilize the stereocilia (By similarity). Acts as a strong inhibitor of PPP1CA phosphatase activity. Recruited to sites of DNA damage and may play a role in DNA damage repair.
Synonyms: C9orf75; FLJ90254; DFNB79
Tractability: Antibody: the Human Protein Atlas places it where antibodies can reach. PROTAC: ubiquitination databases record sites on it; its protein half-life has been measured.
Gene: Protein-coding gene on chromosome 9 (137,191,617 to 137,204,193, reverse strand). Ensembl gene ENSG00000176058.
Subcellular location: Cell projection, stereocilium; Cell projection, microvillus; Nucleus, nucleoplasm; Cytoplasm
Subcellular location (Human Protein Atlas): Plasma membrane
Pathways (Reactome):
Sensory Perception: Sensory processing of sound by inner hair cells of the cochlea; Sensory processing of sound by outer hair cells of the cochlea
Gene Ontology:
Molecular function: protein binding; protein phosphatase 1 binding; protein serine/threonine phosphatase inhibitor activity; actin binding; phosphatase binding; protein phosphatase binding
Biological process: sensory perception of sound; auditory receptor cell stereocilium organization; stereocilium maintenance
Cellular component: cytoplasm; nucleoplasm; microvillus; stereocilium; stereocilium base
Genetic constraint (gnomAD): Loss-of-function variants: 32 observed, 39.11 expected, observed/expected ratio (o/e) 0.82, 90% interval 0.62 to 1.1. The synonymous counts are far from expectation, so gnomAD's model fits this gene poorly and the ratio says little. Missense variants: 1,065 observed, 815.36 expected, observed/expected ratio (o/e) 1.31, 90% interval 1.24 to 1.37. Synonymous variants: 525 observed, 376.08 expected, observed/expected ratio (o/e) 1.4, 90% interval 1.3 to 1.5.
Gene-disease validity (ClinGen):
ClinGen rates the evidence that TPRN causes each of these diseases.
nonsyndromic genetic hearing loss (autosomal recessive): Definitive. A disease characterized by hearing loss that is not part of a larger syndrome.
Homologues: Orthologues: macaque TPRN (93% identical), chimpanzee TPRN (84% identical), mouse Tprn (71% identical), dog TPRN (70% identical), guinea pig TPRN (70% identical), rat Tprn (68% identical), tropical clawed frog tprn (35% identical), zebrafish tprn (33% identical). Paralogues in human: PPP1R18 (19% identical).
Diseases named in the same sentence as TPRN in open-access papers:
TPRN is named in the same sentence as 12 diseases in open-access papers, as found by Europe PMC text mining. Sharing a sentence is not in itself a finding about the gene and the disease. The quoted sentences say what the papers report.
deafness (6 papers, 2014 to 2025). An inherited or acquired condition characterized by the complete loss of the ability to hear from one or both ears. "We show that TPRN-deficient mice have progressive deafness characterized by gradual asynchronous retraction and fusion of outer and inner hair cell stereocilia, followed by synaptic abnormalities." (PMID 40471101, 2025). "Taperin deficiency causes stereocilia disassembly, rootlet breakage at pivots, and other abnormalities culminating in deafness." (PMID 40471101, 2025). "RDX, protein tyrosine phosphatase receptor Q (PTPRQ), and TPRN which are associated with deafness, were mislocalized in fused stereocilia of CLIC5A-deficient mice." (PMID 36035115, 2022). "Taperin, mutations of which lead to deafness in humans, forms a dense-core-like structure encircled by an oligomeric ring of Fam65b at the taper region of stereocilia." (PMID 30380417, 2018). "So far, all reported mutations linked to human deafness are located in exon 1, suggesting it encodes a sequence critical for taperin function." (PMID 30380417, 2018). "Taperin has four exons and all reported mutations linked to human deafness are located in exon 1, suggesting it encodes a sequence critical for taperin function." (PMID 30380417, 2018). "Using purified TPRN and newly engineered mice with total or partial deletions of Tprn, we studied the function of TPRN at the base of stereocilia and the molecular mechanisms of deafness due to a TPRN deficiency." (PMID 40471101, 2025). "However, reduced levels of taperin, which has also been linked to deafness, in Grxcr2-deficient mice restored their hearing and stereocilia morphology." (PMID 35672333, 2022). "In addition to GRXCR2 and taperin, several proteins linked to deafness are concentrated at or near the stereocilia base, including Fam65b, PTPRQ, CLIC5, radixin, and PDZD7." (PMID 30380417, 2018). "Thus, our studies provide leads linking several deafness-related proteins into a common molecular pathway and suggest that targeting taperin is an avenue for treating several forms of hearing loss." (PMID 30380417, 2018). "Thus, our findings demonstrate that GRXCR2 restricts taperin to the stereocilia base, and that mislocalized taperin activity disrupts stereocilia morphogenesis to cause deafness." (PMID 30380417, 2018). "However, loss of TPRN function causes only deafness in mouse and human." (PMID 40471101, 2025).
hearing loss (5 papers, 2018 to 2025). "Taperin, mutations of which have been linked to hearing loss in humans and mice, is a cytosolic protein with 749 aa." (PMID 30380417, 2018). "The mechanism we present here, where GRXCR2 restricts taperin from entering the stereocilia shaft, may also explain the morphological defects and hearing loss caused by mutations of CLIC5, radixin, PTPRQ, MYO6, Fam65b, or other components located at the basal region of stereocilia." (PMID 30380417, 2018). "Beyond the morphological changes caused by the absence of CLIC5, its deficiency has been shown to disrupt the localization of proteins such as RDX, TPRN, and PTPRQ, which are linked to hearing loss." (PMID 40859056, 2025). "ATE1 (Unigene0043244), TPRN (Unigene0030527), TRIOBP (Unigene0033824), GREB1 (Unigene0021168), and DPY19L2 (Unigene0017291) are thought to be related to nonsyndromic hearing impairment by damaging structures in the inner ear." (PMID 31528181, 2019).
nonsyndromic deafness (2 papers, 2010 to 2024). An auditory system disease that is associated with permanent hearing loss caused by damage to structures in the inner ear and/or the middle ear, which is not associated with other signs and symptoms. "The locus TPRN encodes a sensory epithelial protein, and mutations of which cause a progressive course of autosomal recessive nonsyndromic hearing loss." (PMID 37729465, 2024).
lung adenocarcinoma (1 paper, 2024). A carcinoma that arises from the lung and is characterized by the presence of malignant glandular epithelial cells. "To investigate the effect of TPRN His550Gln mutation on tumor progression, we examined proliferation and migration capabilities in both A549 and H1299 lung adenocarcinoma cell lines." (PMID 39432560, 2024).
cancer (1 paper, 2019). A tumor composed of atypical neoplastic, often pleomorphic cells that invade other tissues. "To date, few cancer-related functions of TPRN have been reported." (PMID 31382519, 2019).
TPRN also shares sentences with these, for which no sentence is quoted: breast carcinoma (2 papers); cervical cancer (1); deafness autosomal dominant 10 (1); deafness autosomal recessive 28 (1); Hearing impairment (1); microtia (1); tumor (1).